SOX9 (SRY-box transcription factor 9)
Diseases named in the same sentence as SOX9 in open-access papers (continued):
Sharing a sentence is not in itself a finding about the gene and the disease.
scoliosis (8 papers, 2013 to 2026). A congenital or acquired spinal deformity characterized by lateral curvature of the spine. "Disruptions in the activities of Sox9+, Fgfr3+, or Dlx5+ progenitors at E10.5 may underlie osteogenic conditions such as scoliosis or long-bone deformities." (PMID 40581360, 2025). "Also, functional studies are needed to validate the region, as an enhancer of the SOX9 gene, related to scoliosis and associated phenotypes." (PMID 38245767, 2024). "Some researchers found that the imbalanced expression of sox9, collagen II, collagen X, and aggrecan on both sides of the spine may be the cause of scoliosis." (PMID 30886859, 2019). "FBN1, FBN2, and variants near SOX9, and KCNJ2 are associated with severe scoliosis (greater than 40 degrees)." (PMID 39781499, 2025). "rs12946942 is on chromosome 17q24.3 near the genes SOX9 and KCNJ2, which when mutated cause scoliosis phenotypes." (PMID 24023777, 2013). "rs12946942 may likewise participate in scoliosis pathogenesis by controlling scoliosis-related tissue-specific SOX9 expression." (PMID 27299157, 2016). "We hypothesize that variants in this region may likewise participate in scoliosis pathogenesis by controlling scoliosis-related tissue-specific expression of SOX9 or other genes." (PMID 24023777, 2013). "Interestingly, SOX9 expression is not reduced in the IVD of P10 mutant mice, suggesting that loss of SOX9 expression in the IVD is associated with the initiation of scoliosis." (PMID 34318745, 2021).
atherosclerosis (7 papers, 2021 to 2025). A disease characterized by the build-up of fatty material and calcium deposition in the arterial wall resulting in partial or complete occlusion of the arterial lumen. "The current findings, highlighting a role of SOX9 in aneurysmal disease, align well with the emergent picture of SOX9 as an important culprit in atherosclerosis." (PMID 37561588, 2023). "The expression level of NDUFS3, E-cadherin, BCL2, P21 and SOX9 in atherosclerosis and chronic stress were lower than that in control group." (PMID 37642954, 2023). "This suggests that gene programs activated by SOX9 expression in HUVECs are similar to those that drive EndMT in atherosclerosis." (PMID 35904801, 2022). "Of note, none of the other SOX factors showed the same expression pattern as SOX9, being unique to EC8 and Fibro, suggesting SOX9 is involved in chromatin opening in endothelial cells in lesions to promote a mesenchymal cell phenotype during atherosclerosis." (PMID 35904801, 2022). "We also show that PRG4 and SOX9 induction preceded the formation of macro-calcification nodules in the mouse model of calcific atherosclerosis, supporting the role of PRG4 in early osteogenic modulation during atheroprogression." (PMID 34063989, 2021). "The upregulation of FN1, SOX9 was observed during atherosclerosis." (PMID 36456628, 2022). "Furthermore, our analysis of single-cell data points to SOX9 as a driver of EndMT in atherosclerosis." (PMID 35904801, 2022). "This region is more likely to exhibit the phenotypic transformation of VSMCs during the development and progression of atherosclerosis, suggesting that SOX9 may play a critical role in regulating the phenotypic transformation of VSMCs in atherosclerotic plaques." (PMID 40607212, 2025).
chordoma (7 papers, 2020 to 2025). Chordomas are rare malignant tumors arising from embryonic remnants of the notochord in axial skeleton. "Genes previously implicated in chordoma biology, including CDK6, SOX9, and EGFR, were also recovered." (PMID 37024492, 2023). "SOX9 (n=4, p=0.04), whose knockdown was previously shown to inhibit chordoma cell growth and induce apoptosis, and PARP1 (n=5, p=0.004) and Survivin (n=3,p=0.047), also critical to chordoma cell growth, all show decreased expression with selinexor treatment." (PMID 36059685, 2022). "They reported that a transient siRNA-based SOX9 knockdown in a chordoma cell line leads to enhanced apoptotic activity." (PMID 33076370, 2020). "Genes were selected to represent both those functionally connected to other chordoma dependency genes (PTPN11, FANCM, ADAR, PRKRA, SOX9, SRRM2, SLC2A1, and SLC7A5), as well as those with putatively unique effects (LUC7L2 and CDK6)." (PMID 37024492, 2023). "Additionally, two genes scoring in our screens (TBXT, SOX9) can be classified as lineage-survival dependency genes: these transcription factors mediate normal development of the embryonic notochord, the cell type from which chordoma is hypothesized to originate." (PMID 37024492, 2023). "However, the tumor was finally diagnosed as chordoma based on positive staining for the expression of brachyury, SOX9, and EMA and negative staining for the expression of SOX10." (PMID 35398781, 2022).
colorectal adenoma (7 papers, 2017 to 2025). An adenoma that arises from the colon or rectum. "In most human colorectal adenomas and CRCs, SOX9 is highly expressed, but the correlation between SOX9 overexpression and poor prognosis remains contentious." (PMID 40179020, 2025). "As SOX9 is an oncogene, its upregulation is common in colorectal adenomas and cancer and is an independent indicator of the poor prognosis of CRC." (PMID 33807620, 2021). "The SOX9 gene is overexpressed in both colorectal adenoma and CRC samples compared with normal tissues by 2- and 3.5-fold, respectively." (PMID 31336886, 2019). "We further note that immunostaining for the TEAD4 protein in the Human Protein Atlas database reveals a gradient of expression along the crypt‐villus axis in the human small intestine and colon, and is uniformly induced in human colorectal adenomas, similar to Sox9." (PMID 33950519, 2021). "Notably, six DE-TFs, DACH1, GTF2IRD1, MEIS2, NR3C2, SOX9, and SPIB, were identified as having a dynamic signature along the colorectal adenoma-carcinoma sequence." (PMID 34094897, 2021).
liver disease (7 papers, 2012 to 2025). "We then analyzed the expression of ccn2, a matricellular protein that is upregulated in fibrotic hepatic disorders and sox9/krt19 expression, markers associated with chronic liver damage." (PMID 34413847, 2021). "However, in human liver disease, increasing levels of SOX9 in hepatocyte populations is a prognostic and diagnostic measure that parallels disease severity." (PMID 40489560, 2025). "Similar to our previous work on liver disease, following S. mansoni infection SOX9 was ectopically expressed in activated HSCs, contributing to ECM deposition in the granuloma and hepatocytes surrounding the granuloma." (PMID 40489560, 2025). "The localisation of SOX9 in hepatocytes is reminiscent of our previous work identifying SOX9 positive hepatocytes aligning the scar interface during progressive liver disease, with similarities to the ductal plate during liver development." (PMID 40489560, 2025). "This suggested that not only is Sox9 a dosage-sensitive modifier of the ALGS liver phenotype in mice, but increasing its expression in the liver may be a strategy to improve ALGS liver disease." (PMID 31615106, 2019).
medulloblastoma (7 papers, 2015 to 2025). A malignant, invasive embryonal neoplasm arising from the cerebellum. "Transcriptional regulation by SOX9 has also been associated with the SHH-activated group medulloblastomas." (PMID 34012965, 2021). "Ultimately, they demonstrate that pharmacological suppression of the PI3K/AKT/mTOR pathway destabilizes SOX9 in a GSK3/FBW7-dependent manner, enabling medulloblastoma cells susceptible to cytostatic therapy." (PMID 39974732, 2025). "In medulloblastoma, authors demonstrated that the phosphorylation of SOX9 could be degraded by FBW7." (PMID 39974732, 2025). "Furthermore, SOX9 protein was also targeted by FBXW7 for proteasomal degradation in medulloblastoma cells even under normal unstressed conditions, suggesting that FBXW7-mediated SOX9 degradation might be in a cell and context dependent event, and not specific to DDR." (PMID 34760892, 2021). "SOX9 play an important role in glial fate determination and are commonly overexpressed in WNT and SHH medulloblastoma." (PMID 32508873, 2020). "SOX9 has been reported as a critical transcription factor in MYCN Proto-Oncogene, BHLH Transcription Factor, MYCN-driven medulloblastoma and can be related to drug resistance of these tumors." (PMID 32508873, 2020). "Importantly, differential expression of SOX genes (SOX4, SOX9, and SOX11) in pediatric brain tumors has been used as prognostic marker for disease progression and outcomes in ependymoma and medulloblastoma." (PMID 34012965, 2021). "Additionally, these modules were interconnected via several hub genes, namely, FGFR1, BMP4, PAX6, PAX3, SOX9, and GLI2, all of which have been related to medulloblastomas in previous studies." (PMID 32508873, 2020). "Interestingly, SOX9 might function upstream of GLI2, which is known to be a major effector in the Hedgehog signaling, and act as a key driver of SHH medulloblastomas." (PMID 32508873, 2020).
myocardial infarction (7 papers, 2021 to 2025). Gross necrosis of the myocardium, as a result of interruption of the blood supply to the area, as in coronary thrombosis. "SOX9 has already been reported to promote CF proliferation and migration in vitro, and accordingly, both full body SOX9-deficient and CF-specific SOX9-deficient mice had attenuated cardiac dysfunction and fibrosis after myocardial infarction." (PMID 37154157, 2023). "It has been shown that a subpopulation of activated fibroblasts in heart tissue co-express high levels of CTHRC1 and SOX9 following myocardial infarction." (PMID 40076432, 2025). "In one report, both Cthrc1 and Sox9 gene expression were significantly upregulated in a subpopulation of activated, pro-fibrotic fibroblasts following myocardial infarction in mice." (PMID 40076432, 2025). "In the heart, SOX9 is predominantly expressed in cardiomyocytes and cardiac fibroblasts after myocardial infarction in mice." (PMID 38993791, 2024). "In mice model of acute myocardial infarction, specific inhibition of SOX9 in fibroblasts weaken myocardial inflammation and fibrosis by reducing leukocyte infiltration." (PMID 36977670, 2023). "Revealed that deletion of SOX9 in fibroblasts reduced cardiac fibrosis, thereby improving left ventricular dysfunction, dilation, and myocardial scar formation after myocardial infarction." (PMID 37359552, 2023). "In the heart, SOX9 is predominantly expressed by cardiomyocytes and cardiac fibroblasts after myocardial infarction injury in mice." (PMID 34520400, 2021).
Sepsis (7 papers, 2021 to 2025). Sepsis is defined as life-threatening organ dysfunction caused by a dysregulated host response to infection. "Importantly, molecules involved in this recovery (e.g. Sox9) can be future targets at the bedside and thus have clinical potential to treat sepsis-associated AKI." (PMID 33448928, 2021). "In EZH2 knockout mice, there is a marked reduction in renal inflammation and macrophage infiltration, demonstrating that the downregulation of EZH2 participates in sepsis-induced AKI by upregulating the transcription of sex determining region Y box9 (Sox9)." (PMID 40989844, 2025). "USP7 exacerbates the adverse effects of sepsis on the heart by deubiquitinating SOX9 and leading to an upregulation of its expression." (PMID 38322269, 2024). "In sepsis, the transcription factor SRY-box 9 (SOX9) is highly expressed in cardiac muscle cells, contributing to cardiac damage." (PMID 38322269, 2024). "Our results clearly correlate cell death-immune crosstalk with the development of AKI and demonstrate that knock-down of EZH2 get involved in sepsis-induced AKI by up-regulating the transcription of Sox9." (PMID 37064878, 2023). "EZH2 directly acted on Sox9 to regulate the Wnt/β-catenin pathway and thus affected the apoptosis and inflammatory response during sepsis-induced AKI." (PMID 37064878, 2023). "Targeting the EZH2/Sox9 signaling pathway may offer novel strategies for preventing or ameliorating sepsis-induced AKI." (PMID 40989844, 2025). "Targeting the EZH2/Sox9 signaling pathway may provide new strategies for preventing or ameliorating sepsis-induced AKI." (PMID 37064878, 2023). "Therefore, we verified that the inhibition of EZH2 could regulate the expression of Sox9 by epigenetics to affect sepsis-induced AKI." (PMID 37064878, 2023). "In a murine model of sepsis established via cecal ligation and puncture (CLP), USP7 was shown to enhance SOX9 expression through deubiquitination." (PMID 39803908, 2025). "SOX9, in turn, suppressed miR-96-5p expression by binding to its promoter region, which led to increased NLRP3 expression and exacerbated sepsis-induced myocardial injury and cardiomyocyte death." (PMID 39803908, 2025). "USP7 upregulated SOX9 expression through deubiquitination, and SOX9 suppressed miR-96-5p expression by binding to the miR-96-5p promoter region, thereby promoting NLRP3 expression and then exacerbating sepsis-induced myocardial injury and cardiomyocyte pyroptosis." (PMID 40041174, 2025). "In a model of sepsis-induced AKI, inhibition of EZH2 expression could reduce the apoptotic and inflammatory responses of renal TEC, alleviating AKI by mitigating the transcriptional inhibition of SOX9." (PMID 38169402, 2024).
chondrodysplasia (6 papers, 2013 to 2023). "TRPV4 is a positive regulator of SOX9 and mutations in this gene are linked to chondrodysplasia." (PMID 34663442, 2021). "In a model of metaphyseal chondrodysplasia type Schmid, a chondrodysplasia characterized by short stature and ER stress in the growth plate because of Col10a1 mutations, mice exhibit short stature because of increased expression of Sox9 via ATF4 and CHOP transactivation." (PMID 37796615, 2023). "Moreover, the conditional inactivation of SOX9 in limb buds before mesenchymal condensation resulted in the complete absence of chondrocytes and conditional inactivation of SOX9 after mesenchymal condensation, resulting in severe generalized chondrodysplasia." (PMID 35327578, 2022).
ductal carcinoma in situ (6 papers, 2016 to 2023). "On the other hand, miRNA-140 acts as a tumor suppressor by inhibiting CSCs signaling and cancer initiation through its interaction with SOX2 and SOX9 in both ductal carcinoma in situ (DCIS) and invasive ductal carcinoma (IDC)." (PMID 37958993, 2023). "Furthermore, SFN downregulated SOX9 in ductal carcinoma in situ (DCIS) leading to reduced stem-like cell frequency in vitro and tumor growth in vivo." (PMID 31027362, 2019). "The stem-cell factors sex-determining region Y-related high-mobility group box 9 (SOX9) and aldehyde dehydrogenase 1 (ALDH1), the most activated factors in ductal carcinoma in situ (DCIS) stem-like cells, were identified to be objective targets for miR-140." (PMID 38002007, 2023). "When applied to ductal carcinoma in situ (DISC) cells, miR-140-enriched EVs reduced the Sox9 expression in the DISC cells and blocked cancer progression." (PMID 34069860, 2021).
Hyperglycemia (6 papers, 2011 to 2021). An increased concentration of glucose in the blood. "In contrast, a study using a different Sox9 BAC transgenic line suggested that Sox9+ cells can generate β cells in the context of mild hyperglycemia and long-term administration of EGF and gastrin." (PMID 34421829, 2021). "In vivo reprogramming by administering long-term low-dose gastrin and EGF in hyperglycemia mouse can increase SOX9." (PMID 32118053, 2020). "In an endeavor to understand the negative impact of hyperglycemia and treatment with metformin on alveolar bone repair, the present study evaluated the levels of SOX9, RunX2 and Osterix, transcription factors associated with osteoblast differentiation." (PMID 32841254, 2020). "The expression of SOX9 and RunX2 were also decreased by hyperglycemia and metformin treatment." (PMID 32841254, 2020). "Additionally, gene and protein levels of chondrogenic markers including SOX9, type 2 collagen (Col II) and aggrecan (AGN) were significantly decreased, indicating the chondro-inhibitory nature of hyperglycemia." (PMID 34685425, 2021). "Furthermore, faster decrease of SOX9+ precursor-like cells was noted in 9-day and 16-day DM grafts compared with NDM grafts, implying that hyperglycemia could possibly trigger NPCC progenitor-like cells to differentiate more rapidly." (PMID 29844347, 2018). "Furthermore, the negative impact of hyperglycemia and/or treatment with metformin also could be noted in the initial stages of bone repair, via inhibition of transcription factors Runx2 and Sox9, involved in osteoblast differentiation." (PMID 32841254, 2020).
invasive ductal carcinoma (6 papers, 2014 to 2025). "SOX9 protein, which is normally nuclear, was instead localized in the cytoplasm of 25-30% invasive ductal carcinomas (IDCs) and lymph node metastases." (PMID 28841719, 2017). "Furthermore, increased SOX9 expression in MSC-BRCA+ correlates with prognostic significance in invasive ductal carcinoma and metastatic breast cancer." (PMID 32093026, 2020). "Cytoplasmic SOX9 may serve as a valuable prognostic marker in invasive ductal carcinoma and metastatic breast cancer." (PMID 25109818, 2014).
pancreatic adenocarcinoma (6 papers, 2015 to 2025). "This antigen, defined by two monoclonal antibodies recognising separate epitopes on a large glycoconjugate protein complex, is co-expressed with SOX9 by foregut ductal progenitors in the developing human liver and pancreas, and in pancreatic adenocarcinoma." (PMID 30814526, 2019). "In vitro and in vivo experiments have revealed that SOX9 plays a pivotal role in promoting proliferation, progression, and metastasis of tumor cells, including pancreatic adenocarcinoma (PAAD) cells, by maintaining their stemness and facilitating epithelial–mesenchymal transition." (PMID 40141294, 2025). "Interestingly, analysis in TCGA pancreatic adenocarcinoma data set found a positive correlation between JAG1 and SOX9 expressions, and high SOX9 mRNA level is associated with poor overall survival, whereas low SOX9 expression is associated with significantly longer survival." (PMID 33268505, 2021). "Prospective isolation and molecular and biological characterisation of subpopulations of putative progenitor cells in pancreatic adenocarcinomas will be required to obtain a better understanding of the relationship between progenitor populations marked by GCTM-5, SOX9, LGR5, and DCLK1." (PMID 30814526, 2019).
tendinopathy (6 papers, 2019 to 2021). "Furthermore, immunostaining confirmed tendinopathy-like changes with high percentages of the tendon cells from the ITR group positively stained with SOX-9 and collagen II." (PMID 34322484, 2021). "Elevated expression of SOX-9 and collagen II in tendons were observed in mice subjected to ITR, which matched similar results observed in clinical specimens of excessive mechanical loading-induced tendinopathy." (PMID 34322484, 2021). "The expression of Pparg was higher in the collagenase-induced tendinopathy sample treated with saline injection than in the control group (p < 0.05), but the expressions of the type I and type III collagen genes, Runx2 and Sox9 were similar between the saline-treated and control groups." (PMID 30886307, 2019).
thyroid cancer (6 papers, 2019 to 2026). "In thyroid cancer cells, knockdown of SOX9 has been found to inhibit proliferation, invasion, and EMT." (PMID 31060551, 2019). "For instance, the regulation of thyroid cancer cell migration and invasion by TRIM30 involves targeting SOX17 for K48‐linked polyubiquitination, while E3 ligase E6‐AP affects SOX9 expression through ubiquitin‐mediated degradation, influencing cartilage development." (PMID 40918640, 2025).